SAV1 (salvador family WW domain containing protein 1)
Diseases named in the same sentence as SAV1 in open-access papers (continued):
Sharing a sentence is not in itself a finding about the gene and the disease.
breast cancer (5 papers, 2017 to 2026). A primary or metastatic malignant neoplasm involving the breast. "In contrast, SAV1 mRNA upregulation in breast cancer was associated with a better survival probability, and the elevated expression of the SAV1 protein in pancreatic ductal adenocarcinoma was a significant favorable prognostic factor of overall survival." (PMID 38136317, 2023). "The expression levels of SAV1 and IGF2R were markedly reduced in breast cancer cells compared to MCF10A." (PMID 41511940, 2026). "Experimental validation confirmed the downregulation of key genes such as SAV1 and IGF2R in breast cancer cells." (PMID 41511940, 2026). "Experimental validation confirmed that SAV1 and IGF2R were significantly downregulated in breast cancer cell lines, consistent with public datasets, underscoring their biological relevance." (PMID 41511940, 2026). "By contrast, activation of SAV1 and FRMD6 gene expression using the CRISPRa system led to significant inhibition of mammary tumor growth and strongly reduced tumor size." (PMID 34031411, 2021). "SAV is a scaffold protein containing a WW domain; SAV1 was reported to interact with HAX1 and attenuated its protective role against apoptosis in MCF‐7 breast cancer cells." (PMID 28796930, 2017). "Importantly, when tested in preclinical models of TNBC orthotopic transplantation, the two individual SAV1 and FRMD6 CRISPR-KO were able to significantly facilitate primary mammary tumor growth." (PMID 34031411, 2021). "In the BRCA samples of TCGA, we also noticed a significant relationship between AGR2 expression and FOXA1 gene copy number, as well as several cancer gene copy numbers localized at 14q such as NFKBIA, SAV1, CHD8 or AJUBA, which are not known as driver oncogenes or TSG in breast cancer." (PMID 35857928, 2022).
gastric cancer (5 papers, 2019 to 2024). A primary or metastatic malignant neoplasm involving the stomach. "However, the expression and mechanisms of SAV1 in the development and progression of gastric cancer (GC) remain to be elucidated." (PMID 37033161, 2023).
clear cell renal cell carcinoma (4 papers, 2011 to 2023). "In most pairs of clear cell renal cell carcinoma (ccRCC) patient samples we analyzed, reduced SAV1 expression correlated with high Akt-pT308 signals." (PMID 30944303, 2019). "A clear cell renal cell carcinoma (ccRCC) cell line with homozygous loss of SAV1 has reduced colony-forming capacity when SAV1 is expressed exogenously; additionally, non-tumorigenic renal cells become more proliferative upon SAV1 knockdown." (PMID 25097728, 2014). "Here, the authors show that SAV1, a member of Hippo signalling, interacts with Akt to suppress Akt activity and MERTK-mediated Akt phosphorylation relieves this suppression to facilitate Akt oncogenic activity in clear cell renal carcinomas." (PMID 30944303, 2019).
heart failure (4 papers, 2013 to 2025). Inability of the heart to pump blood at an adequate rate to meet tissue metabolic requirements. "SAV1/2 deletion worsens the response to pressure overload in animal models, unrestricted proliferation of CMs leads to heart failure in models in vivo." (PMID 41213910, 2025). "The Hippo pathway may also suppress cardiomyocyte proliferation via the inhibition of Wnt signaling, and previous reports indicate that the inhibition of Hippo signaling may reverse the progression of heart failure in mice, while SAV1 and LATS1/2 inhibition can improve myocardial recovery." (PMID 32730272, 2020).
liver cancer (4 papers, 2011 to 2023). An epithelial or non-epithelial malignant neoplasm that arises from the liver. "In another study, deletion of both PTEN and SAV1 in the liver promoted the development of liver cancer in mice." (PMID 37033161, 2023). "Mst1/2, Yap, and Sav1 are now clearly established as regulators of liver cancer pathogenesis, yet many questions remain." (PMID 21102585, 2011). "While we did not identify SB inactivation of Ncoa2 and Sav1 in our tumors, these genes were previously identified in liver cancer mouse models driven by SB mutagenesis in the presence of Myc activation or Pten loss." (PMID 33435458, 2021). "Indeed, liver-specific ablation of mouse WW45 (homolog of the human SAV1) gene, an adaptor for the MST kinases, led to increased liver size and expansion of hepatic oval cells and, eventually, liver cancer development." (PMID 22548173, 2012).
renal cell carcinoma (4 papers, 2016 to 2019). "Furthermore, SAV1 downregulation caused by 14q loss confers a survival and growth advantage on renal cell carcinoma (RCC)." (PMID 28968962, 2017). "Thus, our results suggest that both SAV1 and MERTK contribute to Akt activity regulations, and SAV1 is a critical component for MERTK inhibitor-mediated suppression of Akt activation in renal cell carcinoma." (PMID 30944303, 2019). "Moreover, reduced SAV1 expression was observed in renal cell carcinoma (RCC) patients." (PMID 30944303, 2019). "In high-grade clear cell renal cell carcinoma (RCC), the expression of SAV1, an upstream factor in Hippo pathway, was down-regulated." (PMID 26805820, 2016).
colon carcinoma (3 papers, 2017 to 2024). "The expression of YAP, LATS2, Merlin and SAV1 genes were examined in both colon carcinoma cell lines." (PMID 37180710, 2023). "Furthermore, over-expressing miR-590-3p inhibited expressions of LATS1 and SAV1, promoted YAP1 expression and didn’t effect MST1 expression in colon cancer cells." (PMID 28938537, 2017).
colorectal cancer (3 papers, 2019 to 2023). A primary or metastatic malignant neoplasm that affects the colon or rectum. "This study aimed to examine the expression level of the SAV1 gene in colorectal cancer (CRC) and its prognostic value and associations with tumor progression." (PMID 38136317, 2023). "We found that impaired SAV1 expression can be involved in the development and progression of colorectal cancer." (PMID 38136317, 2023). "The salvador family WW domain containing protein 1 (SAV1) is the human homologue of the Salvador protein and was reported to repress human colorectal cancer by inhibiting the Akt-mTOR signaling pathway." (PMID 31848596, 2019). "Another study also showed that miR-103a-3p knockdown suppressed HIF1A expression by targeting the core molecules LATS2 and SAV1 of the Hippo/YAP1 pathway, contributing to reduced proliferation, invasion, migration, glycolysis and angiogenesis in colorectal cancer." (PMID 35094292, 2022).
lymph node metastasis (3 papers, 2015 to 2023). "Second, SAV1 expression was negatively associated with tumor invasion depth, lymph node metastasis, TNM stages, and patient survival." (PMID 37033161, 2023). "Moreover, the expression levels of SAV1 and LATS1 in GC patients with lymph node metastasis were significantly lower than those in GC patients without lymph node metastasis." (PMID 26267324, 2015).
melanoma (3 papers, 2022 to 2024). A malignant, usually aggressive tumor composed of atypical, neoplastic melanocytes. "A study indicates that triptolide can inhibits aggressive melanoma cell growth and metastasis by inducing SAV1 and LATS1 expression and activation of the Hippo pathway." (PMID 38887280, 2024).
pancreas disease (3 papers, 2017 to 2025). "LG-1 cells supported the growth of SAV1, the causative agent of pancreas disease in Atlantic salmon." (PMID 34572091, 2021).
intrahepatic cholangiocarcinoma (2 papers, 2019 to 2025). A carcinoma that arises from the intrahepatic bile duct epithelium in any site of the intrahepatic biliary tree. "In the same line, hepatic inactivation of the MST1/2-adaptor protein SAV1/WW45 resulted in YAP-associated cell proliferation and mutant mice ultimately developed tumors with characteristics of HCC and intrahepatic cholangiocarcinomas (ICC)." (PMID 30931304, 2019). "Interestingly, WES identified SAV1 as a potential driver of Intrahepatic cholangiocarcinoma (ICC)." (PMID 40249565, 2025).
mesothelioma (2 papers, 2020 to 2024). A usually malignant and aggressive neoplasm of the mesothelium which is often associated with exposure to asbestos. "Among the hyper-altered cancer types, mesotheliomas and papillary renal cell carcinomas were the most significant, and this finding was likely related to a high frequency of NF2, LATS2, and SAV1 mutations." (PMID 31959902, 2020).
multiple myeloma (2 papers, 2022 to 2024). "ALKBH5 deficiency in myeloma cells significantly enhanced the SAV1 mRNA methylation level and therefore regulated its stability and expression, led to YAP phosphorylation and finally resulted in YAP deactivation." (PMID 35414790, 2022). "In multiple myeloma (MM), ALKBH5 promotes angiogenesis by elevating salvador family WW domain-containing protein 1 (SAV1) expression and activating the Hippo pathway." (PMID 39098905, 2024). "More importantly, we found that ALKBH5 deficiency in MM cells enhanced the RNA methylation of the HIPPO pathway-initiating protein SAV1, suppressed the activation of the HIPPO pathway, and ultimately reduced the proportion of myeloma stem cells." (PMID 35414790, 2022). "Inhibiting ALKBH5 in MM cells increased SAV1 m6A levels, decreased SAV1 mRNA stability and expression, suppressed the stem cell related HIPPO-pathway signalling and ultimately activates the downstream effector YAP, exerting an anti-myeloma effect." (PMID 35414790, 2022). "Taken together, ALKBH5 inhibition could increase SAV1 m6A levels, suppressed the HIPPO signalling pathway and ultimately activates the transcription factor YAP in myeloma cells, promoted the expression of P21, PUMA and BAX, exerting an anti-myeloma effect in vivo and in vitro." (PMID 35414790, 2022).
ovarian carcinoma (2 papers, 2023 to 2024). A malignant neoplasm originating from the surface ovarian epithelium. "In addition, SAV1 plays an important role in the chemosensitivity of ovarian cancer cells to cisplatin." (PMID 37033161, 2023). "In mice, ovarian cancer development is regulated through YAP, TAZ, MST1/2, SAV1, and LATS1/2 MST1/2 kinases." (PMID 39595118, 2024).
pancreatic ductal adenocarcinoma (2 papers, 2017 to 2023). An infiltrating adenocarcinoma that arises from the epithelial cells of the pancreas. "Immunohistochemical analyses of pancreatic ductal adenocarcinoma showed that a low expression of the SAV1 protein was related to unfavorable clinicopathological features, such as histological differentiation and lymph node status." (PMID 38136317, 2023). "Abnormal expression of the SAV1 gene was reported in some types of human cancers and tumor-derived cell lines such as pancreatic ductal adenocarcinoma and breast and clear cell renal cell carcinoma." (PMID 38136317, 2023). "Here, we determined the role of SAV1 in pancreatic ductal adenocarcinoma (PDAC) development and progression." (PMID 28968962, 2017). "However, despite all these evidences, the role of SAV1 in pancreatic ductal adenocarcinoma development is still unclear." (PMID 28968962, 2017).
renal fibrosis (2 papers, 2016 to 2019). A final common manifestation of a wide variety of chronic kidney diseases characterized by glomerulosclerosis and tubulointerstitial fibrosis. "Given that TGF-β1 treatment increased TAZ protein levels, but not YAP1 protein levels, and that Sav1 depletion activated YAP1/TAZ target gene transcription, we examined TAZ mRNA expression in kidney tissues and assessed the functional role of TAZ in renal fibrosis." (PMID 27550469, 2016).
asthma (1 paper, 2022). "The hippo signaling pathway is mainly composed of MST1/2, LATS1/2, SAV1, MOB1, YAP, or TAZ, and TEAD and is involved in ALI, PAH, pneumonia, IPF, and asthma." (PMID 35443749, 2022).
breast adenocarcinoma (1 paper, 2023). "Moreover, they demonstrated in MCF7 (human breast adenocarcinoma) cells high levels of the SAV1 protein but low levels of the BCL-2 protein." (PMID 38136317, 2023).
cyst (1 paper, 2021). A sac-like closed membranous structure that may be empty or contain fluid or amorphous material. "As an upstream scaffold protein, kidney-specific deletion of Sav1 in mice induced hyperproliferation of renal tubular epithelial cells and cyst formation through activating YAP1." (PMID 34545930, 2021).
glioblastoma (1 paper, 2023). The most malignant astrocytic tumor (WHO grade IV). "In glioblastoma, repressed SAV1 expression promoted the stem cell phenotype of glioblastoma cells." (PMID 37033161, 2023).
glucose metabolism disorders (1 paper, 2023). "In addition, SAV1 KD is postulated to inhibit oxidative stress, organismal death, and apoptosis, and to reduce glucose metabolism disorders." (PMID 36755041, 2023).
Insulin resistance (1 paper, 2023). Increased resistance towards insulin, that is, diminished effectiveness of insulin in reducing blood glucose levels. "Knowledge-based causal analysis prediction algorithms predict SAV1 KD in myoblasts may reduce a variety of abnormal metabolism, ranging from glucose and lipid metabolism disorders to insulin resistance." (PMID 36755041, 2023).
lung adenocarcinoma (1 paper, 2022). A carcinoma that arises from the lung and is characterized by the presence of malignant glandular epithelial cells. "Furthermore, high SAV1 expression conferred better overall survival (OS) in non-small cell lung cancer (NSCLC) comprising lung adenocarcinoma (LUAD) and lung squamous carcinoma (LUSC)." (PMID 35864957, 2022). "The expression of SAV1 was significantly upregulated in BEAS2B cells overexpressing YAP1, however, there was no upregulation in the expression of YAP1 overexpressing lung adenocarcinoma cells HCC827 and lung squamous cell carcinoma cells H2170." (PMID 35864957, 2022).
metastatic disease (1 paper, 2024). "Using immunohistochemical staining of 170 ccRCC patients, VEGFR1 (FLT1) expression was associated with treatment response, histological grade and RECIST (Response Evaluation Criteria in Solid Tumors) score, whereas SAV1 and BLIMP1 (PRDM1) were associated with metachronous metastatic disease." (PMID 38999991, 2024). "There were also correlations between SAV1 and BLIMP1 expression and the presence of metachronous metastatic disease (p = 0.013 and 0.006, respectively), and BLIMP1 expression was found to be associated with male patients (p = 0.048)." (PMID 38999991, 2024).
neuroblastoma (1 paper, 2023). Neuroblastoma (NB) is the most common solid, extracranial childhood tumor. "By contrast, cells of other cell lines such as SH-SY5Y (human neuroblastoma) had very low levels of the SAV1 protein but very high protein levels of BCL-2." (PMID 38136317, 2023).
non-small cell lung carcinoma (1 paper, 2022). A group of at least three distinct histological types of lung cancer, including non-small cell squamous cell carcinoma, adenocarcinoma, and large cell carcinoma. "Herein, we show that YAP activation directly induces transcription of its negative regulator, SAV1, to constitute a negative feedback loop, which plays a vital role in maintaining lung epithelial cell homeostasis and was dysregulated in non-small cell lung cancer (NSCLC)." (PMID 35864957, 2022).
sarcoma (1 paper, 2019). A usually aggressive malignant neoplasm of the soft tissue or bone. "Alterations in various effectors of the Hippo signaling cascade such as YAP1, LATS2 or SAV1 copy number variations have recently been described in a variety of sarcoma subtypes and point to a major role of aberrant Hippo signals in different soft tissue malignancies." (PMID 31873172, 2019).
skin cancer (1 paper, 2025). "Arsenic modulates Hippo pathway activity by upregulating key proteins like Large Tumor Suppressor Kinase 1/2 (LATS1), Salvador homologue-1 (Sav1) and ste20-like kinase 1/2 (Mst1), which are known to play roles in various cancers, including skin cancer." (PMID 40680435, 2025).
steatosis (1 paper, 2023). Increased lipid within the cytoplasm of cells. "In PTEN knockout mice, SAV1 knockdown accelerated steatosis and activated YAP/TAZ while YAP and TAZ deletion prevented PTEN knockout‐induced steatosis." (PMID 37799806, 2023).
thyroid cancer (1 paper, 2022). "Dual-luciferase detection showed that WWC1, SAV1 and LAST2 were direct targets of miR-424-5p in thyroid cancer cells and were negatively correlated." (PMID 35409396, 2022). "Therefore, miR-424-5p suppresses the activity of Hippo signal transduction by targeting WWC1, SAV1 and LAST2, thus promoting lung metastasis and the anoikis resistance of thyroid cancer." (PMID 35409396, 2022).
Ureteral obstruction (1 paper, 2016). Obstruction of the flow of urine through the ureter. "Mice with tubular epithelial cell (TEC)-specific deletions of Sav1 (Salvador homolog 1) exhibited aggravated renal TIF, enhanced epithelial-mesenchymal transition-like phenotypic changes, apoptosis, and proliferation after unilateral ureteral obstruction (UUO)." (PMID 27550469, 2016).